ELK3 (ETS transcription factor ELK3)
Diseases named in the same sentence as ELK3 in open-access papers (continued):
Sharing a sentence is not in itself a finding about the gene and the disease.
cancer (continued). "Combining with a previous study that ELK3 directly represses CDH1 expression in MDA-MB 231, this result indicates that CDH1 might be the main target of miR-200a/ELK3 axis to regulate migration and invasion of cancer cells." (PMID 32414208, 2020). "In addition, ELK3 expression is suppressed by some miRNAs, such as miR-135a and miR-155–5p, to control cancer cell proliferation and angiogenesis." (PMID 32414208, 2020). "Overexpression of ELK3 has been shown to inhibit proliferation of cancer cells." (PMID 31744065, 2019). "Recently, it was demonstrated that ELK3 regulates hypoxia-induced factor 1α (HIF-1α); HIF-1α is a transcription factor that has an essential role in the regulation of genes associated with cancer metastasis, invasion, angiogenesis, cellular proliferation, apoptosis, and glucose metabolism." (PMID 31018569, 2019). "There are several reports about the role of ELK3 in cancer biology." (PMID 31182803, 2019). "However, the literature has showed that SERPINE1 is promoted, not inhibited, by the ETS family members, such as ELK1, Ets-1 and ELK3, in other cancer types." (PMID 26335051, 2015). "ELK3, as a type of ETS protein, was shown to promote cell cycle, proliferation, and EMT, and suppressed cell apoptosis, which could be a promising diagnostic and prognostic biomarker in human cancer." (PMID 38200280, 2024). "Furthermore, we have discovered anti-correlations between hsa-miR-155-5p and ELK3 in some types of cancer, suggesting that this relationship has an important role in some pathologies, which could potentially be exploited for the development of therapies." (PMID 25401928, 2014). "Our research strongly supports the notion that the ELK3-CYFIP2 axis acts as a actin remodeling regulator that drives metastasis of TNBC, influencing both cancer cell migration and immune sensitivity to NK cells." (PMID 39930469, 2025). "The ELK3 gene, also known as NET (Nuclear Protein Related to SAM Pointed Domain-Containing ETS Transcription Factor), has been found to play roles in cancer development and progression." (PMID 37759229, 2023). "ELK3 also regulated the expression of extracellular matrix (ECM) remodeling-related genes, thereby enhancing cancer cell dissemination." (PMID 35409069, 2022). "Inhibitors abrogating FLI1, MEF2C, ELK3, or SP4 activation have been previously shown to have efficacy in different cancers." (PMID 33218352, 2020). "Since cancer cells generally grow in anchorage-independent conditions, we examined the knockdown effects of RSK2 and ELK3 on colony growth in soft agar." (PMID 31018569, 2019). "Our added finding that high ELK3 and ETS2 expression correlates with poor prognosis in human SCCs fuels the importance of this family of proteins in these cancers." (PMID 26590320, 2015). "Thus, the ELK3-CYFIP2 axis plays a pivotal role in regulating actin, emphasizing its significance in controlling both cancer cell migration and NK cell responses in TNBC." (PMID 39930469, 2025). "It highlights that ELK3’s impact on cancer cell proliferation and malignancy is not only mediated through phosphorylation but also through its regulation of protein stability." (PMID 38632244, 2024). "Moreover, in mouse hepatocytes, ELK3-mediated egr-1 regulation has an important role in the epithelial-mesenchymal transition (EMT), a critical event in the process of cancer invasion and metastasis." (PMID 31018569, 2019). "Although in this study we focused primarily on the role of ELK3 in regulating mitochondrial dynamics to explain the chemosensitivity of TNBC cells to CDDP, we do not rule out the possibility that ELK3 also employs alternative mechanisms to regulate the response of cancer cells to chemotherapy." (PMID 37422450, 2023). "However, evidence of ELK3-mediated metastasis in numerous cancer types is lacking." (PMID 35409069, 2022).
infection (3 papers, 2020 to 2022). The state of being infected such as from the introduction of a foreign agent such as serum, vaccine, antigenic substance or organism. "Besides, the downregulation of Elk3 and the downstream induction of Ho1 appeared crucial for the inflammatory response of macrophage function to infection." (PMID 36497272, 2022). "Interestingly, however, the first vhs-dependent gene significantly downregulated in 4sU-RNA of WT infection at 2–3 h p.i. was the ETS transcription factor ELK3, one of three ternary complex factors (TCFs) that act as cofactors of serum response factor (SRF)." (PMID 33148793, 2021). "Notably, ELK3, a TCF cofactor of SRF, was downregulated in a vhs-dependent manner early on in infection." (PMID 33148793, 2021). "While our Western blot analysis of ELK3 protein abundance was inconclusive (data not shown), quantitative proteomics suggested at least a weak change (1.6-fold) between WT and Δvhs infections." (PMID 33148793, 2021).
bacterial infection (2 papers, 2022 to 2025). "Importantly, circTmem241−/−Elk3−/− mice displayed much lower numbers of ILCPs and ILC3s as well as were much more susceptible to bacterial infection than their littermate WT or Elk3−/− mice." (PMID 35953472, 2022).
infectious disease (1 paper, 2022). A disorder directly resulting from the presence and activity of a microbial, viral, or parasitic agent in humans. "We reveal that the circTmem241-Nono-Ash1l-Elk3 axis is required for the ILCP differentiation into ILC3P and ILC3 maturation, which is important to manipulate this axis for ILC development on treatment of infectious diseases." (PMID 35953472, 2022).
neurologic disease (1 paper, 2015). "SAFB1 mediated isoform-specific changes in ANK3, ANKS1B, SAP97 (DLG1), ADD2, KIF16B, and ELK3, as well as in genes linked to the cytoskeleton and/or synaptic function and the aetiology of neurologic disease." (PMID 26694817, 2015).
ELK3 also shares sentences with these, for which no sentence is quoted: lung carcinoma (2 papers); abdominal aortic aneurysm (1); acute lymphoblastic leukemia (1); acute myeloid leukemia (1); adenocarcinoma (1); alcoholic hepatitis (1); aortic aneurysm (1); benign papillomas (1); childhood acute lymphoblastic leukemia (1); diffuse large B-cell lymphoma (1); endothelial dysfunction (1); esophageal cancer (1); esophageal tumor (1); Familial exudative vitreoretinopathy (1); head and neck tumor (1); lymphoid neoplasm (1); malignant glioma (1); malignant mesothelioma (1); multiple myeloma (1); mycosis fungoides (1); retinopathy of prematurity (1); Sezary syndrome (1); skin cutaneous melanoma (1); Stroke (1); T-cell leukemia (1); testicular germ cell tumor (1); thymoma (1).